CD47 (CD47 molecule)
Diseases named in the same sentence as CD47 in open-access papers (continued):
Sharing a sentence is not in itself a finding about the gene and the disease.
cancer (continued). "The finding raises the possibility that the protein stability but not only transcriptional regulation of CD47 might be critical for its involvement in cancer progression." (PMID 36823443, 2023). "In cancer immunotherapy, CD47 inhibition has gained attention as a potential therapeutic strategy." (PMID 38125492, 2023). "Blockade of SIRPα/CD47 interaction is effective in combinational therapy of some cancers." (PMID 36419386, 2023). "CD47-targeted therapies are being evaluated in clinical trials for various cancer types." (PMID 38188674, 2023). "Based on these features, the CD47/SIRP-α axis has become a prominent therapeutic target in cancer." (PMID 38116002, 2023). "scRNA-seq analysis indicated that TNFRSF14 and CD47 were highly expressed in cancer cells, suggesting that CD47 may be better therapeutic targets." (PMID 37021054, 2023). "As recently investigated in mice, WNT/β-catenin signaling blockade might be used in combination with therapeutic strategies, limiting the expression of inhibitory ligands in cancer cells such as CD47 or blocking PD-1/PD-Ls interactions." (PMID 36980226, 2023). "Furthermore, the decreased CD47 expression on cancer cells increases macrophage infiltration in tumors with an enhanced potential to phagocytose cancer cells." (PMID 37275901, 2023). "In this study, we first showed that the activation of GPR84 by the synthetic agonist 6-OAU could synergize with the blockade of CD47 on cancer cells to induce phagocytosis of cancer cells by macrophages." (PMID 36824923, 2023). "However, the precise functions and implications of CD47 in the TME during immunotherapy for cancer patients remain incompletely understood." (PMID 38188674, 2023). "Overall, this comprehensive review highlights the significance of CD47 as a promising target for cancer immunotherapy and provides valuable insight into the challenges and opportunities in developing effective CD47-targeted therapies for cancer treatment." (PMID 38188674, 2023). "This mAb blocks the CD47-SIRPα interaction, leading to increased phagocytosis of cancer cells." (PMID 38188674, 2023). "We hypothesized that high CD47 expression would suppress the growth of GC in the liver by inhibiting phagocytosis of cancer cells by KCs." (PMID 36860925, 2023). "CAR M ability to eliminate cancer cells can be enhanced via mAbs such as anti-CD47 and anti-PD1." (PMID 38017494, 2023). "CD47 molecule is particularly upregulated in some cancer cell lines such as MDA‐231, 4T1 and MCF‐7." (PMID 36925703, 2023). "Chronic DNA damage response in cancer cells might contribute to constitutive elevated expression of CD47 and promote immune evasion." (PMID 36882648, 2023). "However, despite CD47 blockade, certain cancer cells showed resistance to this therapeutic approach." (PMID 37444515, 2023). "As such, CD47 represents a promising immune drug target in cancer immunotherapy." (PMID 37484024, 2023). "Thus, it is expected that the blockade of the CD47-SIRPα axis restores the anti-cancer effect of macrophages." (PMID 36903458, 2023). "Furthermore, in vitro phagocytosis of cancer cells by human macrophages has been shown to be enhanced when monoclonal antibodies were used to block CD47 8,13." (PMID 36860925, 2023). "Cytokine stimulation in HLH patients reduces CD47 expression, interleukin 4 (IL-4), IL-7, and IL-13 influence CD47 expression on Sezary cells, and the expression level of CD47 in cancer cells is regulated by miR-133a, MYC oncogene, and the ERK signaling pathway." (PMID 37241964, 2023). "Several mechanisms have been described to regulate CD47 transcription in cancer cells." (PMID 37958404, 2023). "Targeting cancer cells with CD47 blockage is carried out using four major strategies." (PMID 38033495, 2023). "The highest CD47 expression was observed in the metastatic liver, followed by GC tissues, in which CD47 expression was considerably higher than that in the corresponding para-carcinoma tissue." (PMID 36860925, 2023).
cancer (continued). "Clinical trials also show that CD47 monotherapy is rarely, if ever, effective against human cancer." (PMID 35454837, 2022). "In this study, we performed a pan-cancer analysis between CD47 expression and patients’ prognosis." (PMID 35697717, 2022). "CD47 blockade has emerged as a promising strategy for cancer immunotherapy." (PMID 36230638, 2022). "The raw mRNA expression data of CD47 in cancer patients was downloaded from TCGA and GTEx datasets." (PMID 35697717, 2022). "Our studies to systematically deconstruct the cellular mechanism underlying abscopal responses using in vivo models of SCLC and other cancer types indicate that these responses can be achieved potently and reproducibly by blocking CD47 and activating macrophages." (PMID 36411318, 2022). "Third approach of TAM reprogramming is to promote antigen presentation and phagocytosis of TAMs by blocking anti-phagocytic surface proteins called “don’t eat me” signals, like SIRPα or Siglec-10, with antibodies blocking CD47 or CD24 expressed on cancer cells." (PMID 35211124, 2022). "The percentage of cancer cells with membrane CD47 reactivity ranged from 0–90% (median 20%)." (PMID 35406573, 2022). "CD47 played a vital role in cancer cell proliferation, invasion, and metastasis." (PMID 35697717, 2022). "CD47 is also overexpressed in various types of cancer cells to avoid the innate immune system." (PMID 36291980, 2022). "CD47/SIRPα innate immune checkpoint inhibitors have emerged as a new promising class of cancer immunotherapy that might synergize with treatments that invigorate antitumor T-cell response." (PMID 35538512, 2022). "The CD47 cell surface molecule serves as a myeloid checkpoint: blockade of the interactions between CD47 expressed by cancer cells and SIRPα on the surface of macrophages alleviates a ‘don’t-eat-me’ signal, facilitating the phagocytosis of cancer cells by macrophages." (PMID 36411318, 2022). "Consequently, the novel combination of CD47 and other immune molecules bcould provide new strategies for cancer treatment." (PMID 35697717, 2022). "By contrast, CD47 was among a set of genes showing increased expression in SIRPγhi A549 and H1975 cells compared with SIRPγlo/– cells selected by flow cytometry and SIRPγ-overexpressing cancer cells." (PMID 35229723, 2022). "Cancer cells escape macrophage phagocytosis by exploiting the CD47/SIRPα axis." (PMID 35406573, 2022). "Inhibiting CD47 hinders cancer immune escape and increases phagocytic activity." (PMID 35267626, 2022). "However, many cancer cells hijack this molecular pathway by expressing elevated levels of cell surface CD47 to avoid elimination by phagocytic immune cells." (PMID 35664753, 2022). "Glycolysis inhibition can be particularly effective against cancer cells with a mitochondrial defect or in hypoxic conditions, and the CD47 pathway can also work as a “don’t eat me” signal to macrophage cells, promoting immune escape in certain types of cancer." (PMID 36672796, 2022). "CD47 is an anti-phagocytic receptor that overexpressed in multiple cancer types." (PMID 35757741, 2022). "CD47 is known to promote the growth, invasion, and migration of cancer cells." (PMID 36010209, 2022). "The interaction of CD47 on cancer cells with SIRPα on macrophages could suppress the phagocytosis of macrophages." (PMID 36300110, 2022). "CD47 is a novel potent immunotherapy target in malignancies, targeting CD47 may be a novel strategy for cancer immunotherapy." (PMID 35697717, 2022). "A cancer immunotherapy antibody targeting both CD47 and TIGIT has been patented (WO2020259535)." (PMID 35656508, 2022). "CD47 was expressed in the membrane and cytoplasm of cancer cells." (PMID 35406573, 2022). "The CD47 protein, a member of the membrane protein IG superfamily, is ubiquitously expressed on varieties of types of cellular membranes, especially on senile erythrocytes and cancer cells." (PMID 35557862, 2022). "Taken together, CD47 expression was extensively related to cancer immunity." (PMID 35697717, 2022).
cancer (continued). "We found that extensive membranous CD47 expression by cancer cells characterized 29/98 cases." (PMID 35406573, 2022). "Of note, combination treatment of anti-CD47 and immune checkpoint inhibitors may provide new approaches and improvements for anti-cancer strategies." (PMID 35697717, 2022). "Indeed, blockade or knockdown of CRT had comparable effects in suppressing the anti-CD47 antibody-mediated phagocytosis of cancer cells and abolishing their immunogenicity in mice." (PMID 36497444, 2022). "In addition to PD-1-mediated inhibition, CD47 also serves as an immune evasion mechanism developed by cancer cells." (PMID 35856032, 2022). "We further compared ZL-1201 with the benchmark in a variety of preclinical in vitro studies, and the data showed that ZL-1201 binds CD47 on multiple cancer cells, RBCs, and platelets, and blocks the interaction between CD47 and SIRPα with potency similar to that of the benchmark." (PMID 36970051, 2022). "In addition, HSPA5 was highly expressed in cancer and positively and significantly correlated with CD47 (R = 0.8432, p < 0.0001)." (PMID 35678681, 2022). "For instance, EVs isolated from genetically modified cells overexpressing CD47 hybridized with thermosensitive liposomes loaded with a photothermal agent and an immune adjuvant have been used as a combined photothermal therapy and cancer immunotherapy." (PMID 35214000, 2022). "However, the macrophage cells engineered by protein tyrosine phosphatase in the biosensor engulfed the cancer cells despite the interaction between BMDMs and CD47." (PMID 35794864, 2022). "HIF has been shown to activate highly expressed CD47 in various cancer types." (PMID 36071472, 2022). "In addition to these, ILips showed an increased expression of CD80 (1.5-fold) as compared to free CD-47, indicating that the binding of PTX and CD-47 led to the effective delivery of CD47 to cancer sites along with increased polarization of macrophages." (PMID 36077466, 2022). "On the contrary, inhibiting CD47 expression could increase the ability of macrophages to eradicate different types of cancer." (PMID 35281519, 2022). "Similarly, in mice xenografted with DLD1‐cOVA‐RFP+ cancer cells and treated with CD47 blocking mAb, the popliteal lymph nodes contained more proliferating OT‐I T cells in comparison to IgG treatment." (PMID 35908284, 2022). "Consequently, CD47 predicted poor prognosis in a couple of cancers, however, its prognosis value in many other cancer types need to be investigated." (PMID 35697717, 2022). "Therefore, the engineered monocytes, via blockage of coinhibitory immune signals by rewiring CD47‐SIRPα axis, can be applied to suppress target tumors for cancer immunotherapy." (PMID 35600645, 2022). "In addition, cancers escape ADCP and ADCC by expressing CD47 on the plasma membrane to bind to SIRPα-expressing TAMs to inhibit these anti-cancer mechanisms." (PMID 36077152, 2022). "In light of these obstacles, CD47/SIRPα-targeted BsAbs may be another promising strategy to fight cancer." (PMID 35978372, 2022). "Additionally, a significant positive correlation has been reported between high levels of CD47 expression and a poor prognosis in cancers." (PMID 35978372, 2022). "CD47 is an immunoglobulin overexpressed on the surface of cancer cells." (PMID 36226050, 2022). "Several mechanisms have been proposed to explain regulation of CD47 expression in cancer cells." (PMID 35865547, 2022). "Treatment response largely differs between cancer types and individuals, and this variation could be, in part, the result of differences in CD47 expression between diverse types of cancer." (PMID 36171566, 2022). "However, neutrophils prominently express the myeloid inhibitory receptor SIRPα, which upon interaction with the ‘don’t eat me’ signal CD47 on cancer cells, limits cytotoxicity, forming a mechanism of resistance towards anti-cancer antibody therapeutics." (PMID 35884427, 2022).
cancer (continued). "Furthermore, the level of CD47 was positively correlated with most immune checkpoint genes while also negatively with a few genes in pan-cancer analysis." (PMID 35697717, 2022). "However, CD47 is frequently upregulated on cancer cells compared to normal cells and thus is regarded as an attractive target for cancer immunotherapy." (PMID 35267626, 2022). "Furthermore, the released OXA and PS plus laser irradiation reached a synergic chemo-PDT to induce ICD, and further utilized CD47 blockade to relieve immunosuppression, leading to a combinational strategy for cancer immunotherapy." (PMID 34987658, 2022). "As glycosylation patterns are often uniquely altered in cancer, cancer‐specific glycosylation patterns may be used to selectively target cancer‐expressed CD47." (PMID 35908284, 2022). "The up-regulation of the “don’t eat me” signal, mediated by the CD47 molecule in CSCs, is another mechanism providing the immune escape of CSCs, and it has been shown in several cancers that the blockade of the CD47 signal enables macrophage-mediated phagocytosis of CSCs." (PMID 35269636, 2022). "Finally, we demonstrate that SIRPa knocked-out MDMs can enhance activity against a CD47-expressing cancer cell line." (PMID 36077152, 2022). "In the present study, we found CD47 was closely related to immune cells in various cancers." (PMID 35697717, 2022). "In addition, among these top interactions, we found THBS2/THBS3 secreted by myCAF2 targeting CD47 of cancer cells." (PMID 36352420, 2022). "However, CD47 is not only over-expressed on cancer cells, but also expressed on normal cells, such as ethrocytes." (PMID 35557862, 2022). "We further investigated the correlation of CD47 expression with the level of immune infiltration across a large variety of cancers, and explored whether immune checkpoint genes correlated with CD47 expression in 33 cancer types." (PMID 35697717, 2022). "In light of our observation that SIRPγ is critical for CD47 expression in CSLCs, we asked whether SIRPγ expression influences phagocytosis of the cancer cells by macrophages." (PMID 35229723, 2022). "In addition, CD47 secreted significant levels of IL-10 via M2 macrophages differentiation to promote cancer cell migration." (PMID 35678681, 2022). "To figure out the relation between CD47 and stroma cells of cancers, we analyzed the STROMA Score." (PMID 35697717, 2022). "CD47 overexpression has been described in several types of cancer and, thus, may be predictive of treatment response." (PMID 36171566, 2022). "In addition, there is accumulating evidence that also adaptive T cell-mediated anti-cancer immunity can be promoted by CD47-SIRPα blockade." (PMID 35884427, 2022). "However, its immune evasion mechanisms, characterized by the over-expression of the immune checkpoint molecules PD-L1 and CD47, can be targeted in order to facilitate cancer elimination by cells of innate and adaptive immunity." (PMID 36009390, 2022). "Specifically, we identify a SIRPγhi cell population as a small subset with CSLC properties that transmits the immune escape signal through sustaining CD47 expression in CSLCs and bulk cancer cells, empowering them to escape from macrophage-mediated phagocytosis and leading to tumorigenesis." (PMID 35229723, 2022). "Application of monoclonal antibodies targeting immune checkpoints, such as programmed cell death 1 ligand 1 (PD-L1), integrin-associated protein (CD47) and cytotoxic T lymphocyte associated antigen 4 (CTLA-4) has been found to improve the survival rate of patients with several cancer types." (PMID 35413927, 2022). "Thus, CD47-decorated EVs have longer circulatory half-lives and are more likely to reach their target cancer cells to deliver a therapeutic payload." (PMID 36591444, 2022). "Therefore, disrupting the CD47–SIRPα interaction with anti-CD47 likely promotes the ability of both M1 and M2 macrophages to clear cancer cells." (PMID 36970051, 2022).
cancer (continued). "As the CD47/SIRPα cancer cell/Mφ axis is commonly expressed in NSCLC a therapeutic blockage could prove useful as adjuvant or neo-adjuvant immunotherapy in operable NSCLC." (PMID 35406573, 2022). "Meanwhile, CD47 expression in hepatic cancer stem cells can be inhibited by 4MU, and CD47-SIRPα axis exerts an inhibitory effect on the ability of macrophages to phagocytose cancer cells." (PMID 35410993, 2022). "The CD47/SIRPα axis has emerged as one of the most promising cancer immunotherapy targets." (PMID 35256517, 2022). "In addition to enhancing T cell activation to improve anti-cancer immunity, the checkpoint molecule CD47 acts as an efficient “don’t eat me” signal." (PMID 35418973, 2022). "There are four main mechanisms of CD47 blockade in targeting cancer cells." (PMID 35978372, 2022). "Simultaneously, strong binding to CD47 on cancer cells must be retained." (PMID 35908284, 2022). "Given the expression of CD47 and PD-L1 during tumorigenesis, designed EpCAM-targeted cationic liposomes containing si-CD47 and si-PD-L1 could target EpCAM-rich cancer cells to downregulate both CD47 and PD-L1 proteins." (PMID 36369033, 2022). "The interaction between CD47 and SIRPα on macrophages inhibits phagocytosis, serving as a “don’t eat me” signal, which may counteract pro-inflammatory responses mediated by cancer therapeutic antibodies, reducing therapeutic efficacy." (PMID 35865547, 2022). "Hence, increasing studies have focused on the CD47-SIRPα interaction to achieve better therapeutic efficacy for cancer and other diseases." (PMID 35557862, 2022). "Moreover, additional research discovered the presence of a functional enhancer E7 upstream of the CD47 gene, with increased activity correlating with CD47 overexpression in a number of cancer cell lines." (PMID 35865547, 2022). "In addition, anti-CD47 antibody-mediated phagocytosis of cancer cells by macrophages drives a T-cell-mediated antitumor immune response by priming CD8 T cells." (PMID 36333531, 2022). "The deoxygenation-activated drug tirapazamine (TPZ) was loaded onto Ti3C2 nanosheets, glucose oxidase (GOX), and chloroperoxidase (CPO) to furnish Ti3C2-GOX-CPO/TPZ (TGCT) which was implanted into nanosized cancer cell-derived membrane vesicles with high-expressed CD47 (meTGCT)." (PMID 36296126, 2022). "Future prospective studies will be focusing on the combination of anti-CD47 and immune checkpoint inhibitors or metabolism regulators that could provide an immuno-based strategy for cancer therapy." (PMID 35697717, 2022). "Oncomine database was used to probe into CD47 differential expression at pan-cancer level." (PMID 34966389, 2021). "Therefore, the CD47/SIRPα axis is considered as a novel existing target in immunology, and CD47 will have a major role in tumorigenesis, since its enhanced expression in cancer cells enables evasion of phagocytosis." (PMID 34305918, 2021). "Blocking the CD47 “don’t eat me” signal on cancer cells promotes their phagocytosis by macrophages." (PMID 34625564, 2021). "In the in vitro experiments above, surface-exposed CD47 on cancer cells binds with a monoclonal antibody (B6H12.2), whereas in the body, CD47 would bind with SIRPα, an immune receptor found on macrophages, dendritic cells, and other cells of the innate immune system." (PMID 33540720, 2021). "CD47/SIRPα crosstalk has been conceptually chosen to develop NPs that could efficiently block cancer resistance to macrophage-mediated phagocytosis." (PMID 34575416, 2021). "Interestingly, various types of cancer seem to express high levels of CD47 to escape uptake by phagocytes." (PMID 34831455, 2021). "Cancer cells may escape the immune surveillance of macrophages by upregulation of CD47 expression which dampens innate immune response; this assumption makes CD47 inhibition a plausible treatment strategy for patients with LNET." (PMID 34195295, 2021). "Studies of several cancer types have suggested prognostic properties of CD47 overexpression." (PMID 34944850, 2021).